RPL10L (ribosomal protein L10 like)
Description:
Testis-specific component of the ribosome, which is required for the transition from prophase to metaphase in male meiosis I (By similarity). Compensates for the inactivated X-linked RPL10 paralog during spermatogenesis. The ribosome is a large ribonucleoprotein complex responsible for the synthesis of proteins in the cell. The male germ cell-specific ribosome displays a ribosomal polypeptide exit tunnel of distinct size and charge states compared with the classical ribosome (By similarity). It is responsible for regulating the biosynthesis and folding of a subset of male germ-cell-specific proteins that are essential for the formation of sperm (By similarity).
Synonyms: RPL10_5_1358; SPGF63
Tractability: Small molecule: a structure with a bound ligand is known. PROTAC: ubiquitination databases record sites on it.
Gene: Protein-coding gene on chromosome 14 (46,651,010 to 46,651,781, reverse strand). Ensembl gene ENSG00000165496.
Subcellular location: Cytoplasm
Subcellular location (Human Protein Atlas): Cytosol; Endoplasmic reticulum
Pathways (Reactome):
Metabolism of proteins: Eukaryotic Translation Termination; Formation of a pool of free 40S subunits; GTP hydrolysis and joining of the 60S ribosomal subunit; L13a-mediated translational silencing of Ceruloplasmin expression; PELO:HBS1L and ABCE1 dissociate a ribosome on a non-stop mRNA; Peptide chain elongation; Ribosome Quality Control (RQC) complex extracts and degrades nascent peptide; SRP-dependent cotranslational protein targeting to membrane; ZNF598 and the Ribosome-associated Quality Trigger (RQT) complex dissociate a ribosome stalled on a no-go mRNA
Metabolism of RNA: Major pathway of rRNA processing in the nucleolus and cytosol; Nonsense Mediated Decay (NMD) enhanced by the Exon Junction Complex (EJC); Nonsense Mediated Decay (NMD) independent of the Exon Junction Complex (EJC)
Cellular responses to stimuli: Response of EIF2AK4 (GCN2) to amino acid deficiency
Developmental Biology: Regulation of expression of SLITs and ROBOs
Disease: Viral mRNA Translation
Metabolism: Selenocysteine synthesis
Gene Ontology:
Molecular function: structural constituent of ribosome
Biological process: spermatogenesis; male meiosis I; ribosomal large subunit assembly; translation
Cellular component: cytosolic large ribosomal subunit; membrane; nucleus; ribosome; cytoplasm
Genetic constraint (gnomAD): Loss-of-function variants: 12 observed, 14.27 expected, observed/expected ratio (o/e) 0.84, 90% interval 0.54 to 1.36. The upper end of that interval is the gene's LOEUF score, 1.36, which puts it in group 5 of 6, group 1 being the genes least tolerant of losing a copy. Missense variants: 320 observed, 303.64 expected, observed/expected ratio (o/e) 1.05, 90% interval 0.96 to 1.16. Synonymous variants: 120 observed, 105.75 expected, observed/expected ratio (o/e) 1.13, 90% interval 0.98 to 1.32.
Homologues: Orthologues: chimpanzee RPL10L (99% identical), macaque RPL10L (99% identical), mouse Rpl10l (95% identical), rat Rpl10l (95% identical), dog RPL10L (94% identical), rabbit RPL10L (94% identical), tropical clawed frog rpl10 (92% identical), guinea pig RPL10L (89% identical), zebrafish rpl10 (88% identical), pig RPL10L (79% identical), Drosophila melanogaster RpL10 (76% identical), Caenorhabditis elegans rpl-10 (71% identical). Paralogues in human: RPL10 (96% identical).
Diseases named in the same sentence as RPL10L in open-access papers:
RPL10L is named in the same sentence as 5 diseases in open-access papers, as found by Europe PMC text mining. Sharing a sentence is not in itself a finding about the gene and the disease. The quoted sentences say what the papers report.
male infertility (4 papers, 2021 to 2024). The inability of the male to effect fertilization of an ovum after a specified period of unprotected intercourse. "Rpl10l is required for male meiotic division and Rpl10l-deficient mice exhibited spermatogenic failure and male infertility." (PMID 36831240, 2023). "Furthermore, the deficiency of Rpl10l, a gene with testis-specific expression, can disturb ribosome biogenesis in late-prophase spermatocytes and prohibit the transition from prophase into metaphase of the first meiotic division, resulting in male infertility." (PMID 38012716, 2023). "Previously knockout of such types of retrogenes, including Cetn1, Cstf2t, Pgk2 and Rpl10l, always resulted in spermatogenic abnormalities and male infertility." (PMID 34249105, 2021). "Interestingly, RPL10L is essential for meiotic processes, while mutations in PPL10L lead to male infertility." (PMID 39086661, 2024).
ovarian carcinoma (2 papers, 2009 to 2011). A malignant neoplasm originating from the surface ovarian epithelium. "The RPL10L gene is related to ovarian cancer and JMJD1C plays an essential role in embryogenesis and carcinogenesis." (PMID 21533145, 2011). "We tested for the expression of five of the known retrogenes, UTP14C, PGK2, RPL10L, RPL39L and UBL4B in normal human ovary and ovarian cancers." (PMID 19333399, 2009).
liposarcoma (1 paper, 2021). A usually painless malignant tumor that arises from adipose tissue. "In liposarcoma, NIP7, RPL10L, and MCM2 are significantly associated with long-term no recurrence survival rate." (PMID 34712323, 2021).
cancer (1 paper, 2019). A tumor composed of atypical neoplastic, often pleomorphic cells that invade other tissues. "Moreover, MLNR, IGHE and RPL10L are only obtained by MVSPL, these genes are targets for cancer drugs." (PMID 31534156, 2019).
RPL10L also shares sentences with these, for which no sentence is quoted: infection (1 paper).